BRAF (B-Raf proto-oncogene, serine/threonine kinase)
Diseases named in the same sentence as BRAF in open-access papers (continued):
Sharing a sentence is not in itself a finding about the gene and the disease.
cutaneous melanoma (continued). "Similar to cutaneous melanoma, immune checkpoint inhibitors and BRAF/MEK inhibitors are used as the first-line treatment for metastatic NAM, but data on the efficacy of these therapies remain scarce." (PMID 36983205, 2023). "The American Society of Clinical Oncology (ASCO) guidelines have recommended nivolumab and pembrolizumab as adjuvant systemic therapies for patients with resected stage-IIIA/B/C/D cutaneous melanoma harboring wild-type BRAF." (PMID 38139110, 2023). "Although chemotherapy has been widely studied and used in the historical treatment of cutaneous melanoma, its current utility is limited considering the significant superiority of ICIs and BRAF/MEKis." (PMID 36988735, 2023). "Like in skin melanomas, the frequency of CNAs in CMs appears to vary depending on the genetic background and has been shown to be relatively higher in BRAF/NRAS-wildtype tumors." (PMID 37761808, 2023). "Vemurafenib is commonly used as a standard drug for targeting the treatment of skin melanoma, particularly inhibiting BRAF proteins." (PMID 37813639, 2023). "Like in skin melanomas, NRAS and BRAF mutations are predominantly mutually exclusive in CMs, suggesting that the activating mutations in either of these two key molecules constitute the major oncogenic drivers through the MAPK (RAS/RAF/MEK/ERK) pathway." (PMID 37761808, 2023). "As expected, patients with non-cutaneous melanoma, higher LDH, and higher ECOG performance status exhibited shorter median time to death, while those carrying BRAF mutations exhibited a longer median time to death." (PMID 37388743, 2023). "In cutaneous melanoma, inhibitors of the BRAF (BRAFi) and MEK (MEKi) kinases (e.g., vemurafenib and cobimetinib) are prototypical of highly effective targeted anti‐cancer drugs." (PMID 36700386, 2023). "BRAFV600E or closely related mutations (e.g., BRAFV600K) are found in ~50% of cutaneous melanomas and RAF/MEK therapy is the first line treatment option for BRAF‐mutant metastatic melanoma." (PMID 36700386, 2023). "The prototype for targeting BRAF V600E/K is cutaneous melanoma, where 40–60% of patients with these mutations are eligible for the FDA-approved BRAF-inhibitor, vemurafenib." (PMID 36900212, 2023). "Here, we used the TWM term for cutaneous melanomas where all the major oncogenic drivers are wild type: BRAF, RAS and KIT." (PMID 36980598, 2023). "Like in skin melanomas, NF1 mutations can co-exist with either NRAS or BRAF mutations in CMs, albeit infrequently." (PMID 37761808, 2023). "Between 1 July 2018 and 31 December 2021, 717 resectable stage III BRAF-mutant cutaneous melanoma patients were included in the DMTR." (PMID 36672358, 2023). "The use of risk prediction models for the precision immune treatment of patients with BRAF V600E WT and BRAF V600E-mutant skin cutaneous melanoma (SKCM) is an issue worth exploring." (PMID 36704723, 2023). "For example, among the top three exclusively mutated gene pairs are BRAF and NRAS in skin cutaneous melanoma (p = 1.1 × 10–44), KIT and PDGFRA in gastrointestinal stromal tumour (p = 3.3 × 10–37), and EGFR and KRAS in lung adenocarcinoma (p = 6.6 × 10–29)." (PMID 37550388, 2023). "In mucosal melanoma, mutations in BRAF (12.0%) and NRAS (8.0%) were both lower than that in western population, and lower than Chinese cutaneous melanoma." (PMID 35688842, 2022). "In BRAF WT skin melanoma, patients expressing high levels of DUSP4 mRNA had a better response to selumetinib." (PMID 36576731, 2022). "Recurrent RAC1/P29S in primary cutaneous melanomas has often been shown in conjunction with mutant BRAF, and possibly aggravates BRAF-dependent disease progression." (PMID 35454871, 2022).
cutaneous melanoma (continued). "Addition of TERT promoter mutation targets in the custom panel was predicted to further increase coverage by ~15% in those cutaneous melanoma patients that are NRAS or BRAF WT." (PMID 35494035, 2022). "We reported a prospective multi-centre study to explore systemic therapy sequencing and its impact on OS in patients with metastatic BRAF-mutant cutaneous melanoma." (PMID 35323326, 2022). "In CJM and in cutaneous melanoma, BRAF and MEK inhibitors have mainly been used in a metastatic setting." (PMID 35326726, 2022). "In this regard, the Cancer Genome Atlas (TCGA) program has established a framework of genomic classification for cutaneous melanomas as BRAF, NRAS, NF1, and Triple Wild-Type (WT), and serves as a guide when making decisions about therapy." (PMID 35844619, 2022). "As was shown, there are three major driver oncogenes defining three major molecular forms of skin melanoma, BRAF-, NRAS- and KIT-mutant, and there is a fourth which is the so-called triple wild-type form." (PMID 35628196, 2022). "In cutaneous melanoma TERT promoter mutations commonly co-occur (80-90%) with NF1, BRAF or NRAS mutations, and TERT promoter mutations are also found in 15-60% of BRAF/NRAS/NF1 WT cutaneous melanoma background." (PMID 35494035, 2022). "These two studies have verified the clinical impact of ctDNA BRAF V600E SNV detection for cutaneous melanoma patients." (PMID 35205608, 2022). "The phase II study in patients with metastatic BRAF-mutant cutaneous melanoma, previously treated with BRAF or other types of inhibitors, reported an ORR of 25% and median PFS of 4 months in the group without previous BRAFi therapy." (PMID 36358912, 2022). "BRAF is a kinase that belongs to the BRAF-MEK-ERK signaling pathway (MAPK pathways) and is mutated in approximately 60% of skin melanoma cases." (PMID 35565444, 2022). "In this study, we defined a gene signature based on the top 200 most significantly upregulated genes in BRAF V600E versus BRAF wild‐type samples from primary skin cutaneous melanoma data in the TCGA dataset." (PMID 35044091, 2022). "Approximately 50–60% of cutaneous melanomas demonstrate the expression of mutant BRAF, and have been targeted by BRAF, and MEK inhibitors." (PMID 35624662, 2022). "A 68-year-old man, without a family history of cancer, was diagnosed with a pT2N0M0 BRAF (v-raf murine sarcoma viral oncogene homolog B1) wild type primary cutaneous melanoma of the scalp in April 2017." (PMID 35919234, 2022). "Mature data from several phase III randomized controlled trials (NCT02631447 and NCT02224781) would be required to definitively determine optimal systemic therapy sequencing for the management of metastatic BRAF V600-mutant cutaneous melanoma patients." (PMID 35323326, 2022). "The main genetic drivers for cutaneous melanoma are B-Raf proto-oncogene (BRAF), neurofibromin 1 (NF1), and neuroblastoma RAS viral oncogene homolog (NRAS) mutations, which are primarily mutually exclusive in primary tumours." (PMID 35884596, 2022). "Clinically and histologically, conjunctival melanomas, which harbour mutations in BRAF and NRAS, show greater similarity to cutaneous melanoma than does UM." (PMID 35682684, 2022). "In a phase IIa study (NCT02083354) of patients with unresectable or metastatic BRAF V600-mutant acral/cutaneous melanoma treated with dabrafenib (150 mg twice daily) with trametinib (2 mg once daily), treatment sequencing results were collected." (PMID 35565255, 2022). "Among them, the most common allelic variant at a specific nucleotide is the BRAF V600 SNV, which accounts for 40–50% of cutaneous melanoma patients." (PMID 35205608, 2022). "Cutaneous melanoma largely depends on MAPK-signaling, with roughly half of patients harboring the V600E/K activating mutation in BRAF protein." (PMID 36271142, 2022).
cutaneous melanoma (continued). "Eight (33%) of the cutaneous melanoma samples had additional NGS-identified mutations, of which four possessed BRAF variants that cannot be identified by the Idylla system, two of which were Tier 1 mutations." (PMID 35627184, 2022). "In cutaneous melanoma, the most frequently mutated driver gene is the RAS effector BRAF, which is altered in 50% of cases." (PMID 35234863, 2022). "This initial study demonstrated that BRAF AV in ctDNA is detectable, and the clinical importance of ctDNA BRAF AV monitoring to predict treatment responses and survival for cutaneous melanoma patients." (PMID 35205608, 2022). "In skin melanoma cell lines, Ganetespid induced downregulation of the MAPK signaling pathway both in BRAF- and NRAS mutated cell lines." (PMID 35326726, 2022). "The identification of MAPK kinase activation upon AKA kinase inhibition in skin melanoma cell lines also led to the suggestion of combining AKA inhibition with BRAF or MEK inhibitors to overcome potential resistance." (PMID 35326726, 2022). "MAPK signaling is overactive in the majority of CMs, driven by activating mutations in BRAF (~50%) or NRAS (~25%), or loss of function mutations in NF1 (~15%) (Genomic Classification of Cutaneous Melanoma, 2015)." (PMID 35513054, 2022). "We identified BRAF V600E (11/25; 44%) as the most commonly mutated gene, followed by NRAS (2/25; 8%), and KRAS (1/25; 4%) in cutaneous melanomas." (PMID 34102999, 2021). "Cutaneous melanomas are classified into four genetic subtypes based on TCGA (The Cancer Genome Atlas): BRAF mutant, RAS mutant, NF1 mutant, and triple WT (wild-type)." (PMID 34290710, 2021). "Analysis of BRAF V600K-mutant cutaneous melanoma samples from the Cancer Genome Atlas highlighted, with respect to V600E, an upregulation of energy metabolism, emphasizing their clinical aggressiveness." (PMID 33801689, 2021). "Mutations that upregulate the pathway, including BRAF (B rapidly accelerated fibrosarcoma kinase), RAS (rat sarcoma virus small GTPase), and NF1 (neurofibromin 1), are found in more than 80% of cutaneous melanomas." (PMID 35008286, 2021). "Dabrafenib combined with trametinib confer long-term survival in Chinese patients with BRAF V600-mutant, unresectable or metastatic acral/cutaneous melanoma." (PMID 34504796, 2021). "BRAF inhibitors (BRAFi) selectively target oncogenic BRAFV600E/K and are effective in 80% of advanced cutaneous malignant melanoma cases carrying the V600 mutation." (PMID 34040017, 2021). "In cutaneous melanoma, the presence of a TERT promoter mutation in addition to a BRAF mutation is associated with unfavorable clinicopathological characteristics, such as large tumor thickness and a high mitotic rate." (PMID 34071371, 2021). "Upregulation of the YAP/TAZ pathway was found in cutaneous melanoma tissue of patients who developed resistance to BRAF-inhibitor or RAF + MEK-inhibitor therapy." (PMID 33798262, 2021). "Mutations in KIT, NF1 and SF3B1 genes are more frequently seen in mucosal melanomas, while alterations to NRAS and BRAF genes are more common in cutaneous melanomas." (PMID 34209084, 2021). "Approximately 50% of cutaneous melanoma patients are mutant in BRAF gene, 15–20% of patients are positive for NRAS damaging mutations both leading to a constitutively enhanced MAPK pathway activity." (PMID 34885093, 2021). "We identified no convincing effect of VP in the two CoM cell lines with either a BRAF or NRAS mutation (CRMM1 and CRMM2), whereas the cutaneous melanoma cell line OCM3 did show a response to VP." (PMID 33798262, 2021). "Recently, there have been major advancements in the treatment of cutaneous melanoma, due to the introduction of targeted therapies, including for example vemurafenib and dabrafenib (BRAF kinase inhibitors) and trametinib and cobimetinib (MEK inhibitors)." (PMID 34123788, 2021). "Commonly to cutaneous melanoma, mucosal mutations shows alterations in SF3B1, KIT, and NF1 and less frequently mutations in BRAF and NRAS." (PMID 33918490, 2021).
cutaneous melanoma (continued). "Again, our findings regarding CYSLTR2 p.L129Q show similarities to BRAF p.V600E in cutaneous melanoma." (PMID 33588787, 2021). "Using a CRISPR activation screening, we identified genes involved in BRAF inhibitor (BRAFi) resistance in cutaneous melanoma." (PMID 33724679, 2021). "V-raf murine sarcoma viral oncogene homolog B (BRAF) and neuroblastoma RAS viral oncogene homolog (NRAS) mutations are different in mucosal melanomas in comparison to cutaneous melanomas." (PMID 34571863, 2021). "The management of unresectable and metastatic cutaneous melanoma has substantially improved with the introduction of molecular targeted therapy (BRAF and MEK inhibitors) and immunotherapy (Immune checkpoint inhibitors)." (PMID 34831002, 2021). "Anti-BRAF and anti-MEK targeted therapies prescribed in combination have revolutionised the treatment of BRAF-mutated cutaneous melanoma." (PMID 34198863, 2021). "The phylogenetic trees of cutaneous melanoma samples with amplification of BRAF express a major dominant clone, with only rare intermediates that are persistent from the previous selective sweeps, consistent with a linear evolutionary process." (PMID 33801689, 2021). "A recent phase IIa trial evaluated the efficacy and safety of dabrafenib plus trametinib in 77 East Asian patients with unresectable or metastatic BRAF V600-mutant cutaneous melanoma, including 61 (79.2%) from China’s mainland." (PMID 34504796, 2021). "In mucosal melanoma, BRAF and NRAS mutations are far less frequent compared to cutaneous melanoma, while mutations in c-KIT are observed in 7–25% of cases." (PMID 33233603, 2020). "The genetic spectrum of conjunctival melanoma, however, includes frequent mutations in the BRAF, NRAS and TERT promoter genes, which are found in cutaneous melanoma as well." (PMID 33396957, 2020). "Following BRAF and NRAS, NF1 is the third gene most commonly mutated in cutaneous melanoma (in about 17% of the cases) and frequently co-occurs with mutations in the RASA2 gene." (PMID 33003469, 2020). "On the basis of exome and genome sequencing studies, BRAF and NRAS were identified as the most commonly mutated genes in cutaneous melanoma patients." (PMID 31549767, 2020). "On the other hand, hotspot mutations in the genes BRAF and NRAS, in combination with homozygous deletions of the gene CDKN2A, were frequently found in cutaneous melanoma." (PMID 32825510, 2020). "Vemurafenib is a potent inhibitor of genetically activated BRAF, which is responsible for tumoral proliferation in cutaneous melanoma." (PMID 32167264, 2020). "Based on the IC50 obtained for NHC-Pt-I2 after 1 h exposure of BRAF-m or BRAF-wt skin or lymph node metastatic cutaneous melanoma cells, we believe that NHC-Pt-I2-containing chemotherapies delivered at a low dose would be an interesting approach." (PMID 33105692, 2020). "This panel encompassed two mutually exclusive genetic subsets of cutaneous melanoma, since MeWo and HMCB are BRAF-wt and NRAS mutated (NRAS-m), A375 and SK-MEL-28 are BRAF-m and NRAS wildtype (NRAS-wt)." (PMID 33105692, 2020). "WES of 103 cutaneous melanomas, including 77 tumor samples and 26 cell lines, found FBXW7 mutations (8.1%) independently of BRAF or NRAS mutation." (PMID 32850962, 2020). "The second case, patient M.G., was a 51-year-old male with BRAF wildtype cutaneous melanoma, who developed liver metastases and was treated with ipilimumab with progressive disease." (PMID 32117727, 2020).
cutaneous melanoma (continued). "The timing of such molecular assessment in patients with cutaneous melanoma will be discussed, and we will also examine considerations and approaches for accurate and effective BRAF testing." (PMID 32695793, 2020). "The introduction of vemurafenib and other BRAF inhibitors has been a great improvement in the treatment of advanced cutaneous melanoma." (PMID 32167264, 2020). "Mutations of the oncogenes BRAF and NRAS are the most common genetic alterations in cutaneous melanoma and the prognostic significance of the mutations shows differently." (PMID 31649871, 2019). "We show that in addition to being less frequent, BRAF and NRAS mutations are different in mucosal melanoma compared to cutaneous melanomas." (PMID 31398831, 2019). "In the absence of recognized therapeutic options for metastatic CoM and with extensive evidence from cutaneous melanoma (with which CoM shares many characteristics), BRAF and PD‐1 inhibitors provide rational current treatment options." (PMID 30672666, 2019). "The frequency of BRAF, NRAS and KIT mutations in CjM is more similar to cutaneous melanoma than uveal/mucosal melanoma." (PMID 31683701, 2019). "According to the most prevalent significantly mutated genes, The Cancer Genome Atlas Network recently provided a schema for cutaneous melanoma genomic classification into four subtypes: mutant BRAF, mutant RAS, mutant NF1, and triple-WT (wild-type)." (PMID 31717496, 2019). "With UM being a rare melanoma, numbers of tumours are unnecessarily checked for BRAF mutational status, and many patients undergo 18F-Fluorodeoxyglucose PETCT and receive immunotherapy as for cutaneous melanoma." (PMID 31200439, 2019). "LncRNAs were assessed in the plasma of pretreated BRAF-mutated unresectable stage III and IV cutaneous melanoma patients and healthy donors in order to assess their potential as biomarkers of BRAF inhibitor treatment efficacy." (PMID 31231466, 2019). "In our study, which was based on a human model and immunohistochemical staining, there was a high frequency of BRAF V600E expression in malignant skin melanoma with significant differences between them and examined nevi (P<0.001)." (PMID 31531096, 2019). "This would explain the high frequency of NRAS Q61 and BRAF V600 mutants in cutaneous melanoma where the MAPK pathway is playing such a significant role." (PMID 31398831, 2019). "In vitro, Vemurafenib and Dabrafenib inhibit BRAF-mutant CjM cell lines, similarly to cutaneous melanoma cells." (PMID 31683701, 2019). "All of the malignant skin melanoma cases showed immunoreactivity with BRAF V600E in immunohistochem- ical staining, 60% showed high intensity (score +3) and the remaining 40% showed low intensity (score 1+ and 2+)." (PMID 31531096, 2019). "Vemurafenib, the v-Raf murine sarcoma viral oncogene homolog B (BRAF) inhibitor was the first new generation drug approved for skin melanoma treatment." (PMID 31231466, 2019). "BRAF and NRAS genes, which encode mitogen-activated protein kinase (MAPK) pathway constituents, are recurrently mutated in cutaneous melanoma." (PMID 29992995, 2018). "Cutaneous melanoma can be classified into four different genomic subtypes: mutant BRAF, mutant RAS, mutant NF1, and triple-WT (wild-type)." (PMID 29929490, 2018). "These included 11 BRAFV600-mutant, 10 NRAS-mutant and 10 BRAF/NRAS wild type (BRAF/NRASWT) cutaneous melanoma cell lines, and 8 GNAQ/11-mutant UVM cell lines." (PMID 29977240, 2018). "Therefore, it is possible to hypothesize that specific genotypes, including the TERT –245T>C polymorphism, besides the debated SNPS in MC1R (not confirmed by the present study), may influence the occurrence of somatic BRAF mutations in individuals who develop cutaneous melanoma." (PMID 29464027, 2018). "One patient (male, age 68 years) with BRAF L597R cutaneous melanoma, who received TAK-733 at 16 mg, had a partial response that was reported at cycle 4 and maintained until cycle 8 (approximate duration of 4 months)." (PMID 27650277, 2017).